JUNB (JunB proto-oncogene, AP-1 transcription factor subunit)
Diseases named in the same sentence as JUNB in open-access papers (continued):
Sharing a sentence is not in itself a finding about the gene and the disease.
tumor (continued). "Multiple lines of transcriptomic evidence in tumor-educated THP1 cells point to STAT3 pathway activation, including upregulation of canonical STAT3 targets (SOCS3, CISH, BCL3, JUNB, PIM1) and increased expression of STAT3-activating ligands (IL6, IL11, LIF, OSM) in response to TNBC contact." (PMID 41514627, 2025). "Through a comprehensive workflow combining H3K27ac-ChIP-seq and RNA-seq analyses, we identified critical TFs and tumor-specific super-enhancer domains (T-SEDs) that regulate gene expression in HPV+ HNSCC, such as TP63, SMAD3, FOSL2, JUND, JUNB, KLF5, and TFAP2A." (PMID 41323280, 2025). "Consistent with the results from non-tumor samples, all the TIMGs that we identified (ENO1, MUC1, COL5A1, COL11A1, IL11, AIM2, JUNB) as well as FABP7, exhibited significantly or moderately elevated expression in multiple TCGA tumors, including GBM, compared to normal tissues." (PMID 39596296, 2024). "Indeed, JUNB and JUNA are found critical downstream effectors of the tumor suppressor activity of another ETS gene family SPI1/PU.1, and that reduced expression of JUNB shown to be a common feature of acute myeloid leukemogenesis." (PMID 38461240, 2024). "Furthermore, previous mechanistic studies have shown that JUNB overexpression regulates the mitochondrial apoptosis pathway, mediating resistance to FasL and TRAIL-induced cell death, and thus tumor resistance to immunotherapy." (PMID 39430754, 2024). "In addition, abnormal tumor TNF pathways mediated by abnormal expressions of TNF, NF-κB, FOS, JUN, and JUNB were observed, and scATAC-seq results confirmed the presence of abnormal accessibility binding sites for the transcription factors FOS, JUN, and JUNB." (PMID 38770048, 2024). "Our results showed that compared to the control group, MZ-1 or doxycycline alone decreased the tumor size and consequently prolonged mouse survival; and that dual targeting of MYC and JUNB by MZ-1 and doxycycline, respectively, significantly enhanced their anti-MM activity." (PMID 39160158, 2024). "We also show that high levels of JUNB switch the response of TGF-β2 stimulation from an antiproliferative to a pro-invasive one, induce endogenous TGF-β2 production by promoting TGF-β2 mRNA translation, and enhance tumor growth and metastasis in mice." (PMID 36494864, 2022). "Breast cancer is pathologically demarcated by a plethora of abnormal gene profiles and transcripts that drive tumor initiation (MYC, Erb-B2 Receptor tyrosine kinase 2 (ERBB2), tumor progression (FOS, JUNB), proliferation and metastasis (epidermal growth factor receptor (EGRF))." (PMID 34299315, 2021). "In line with our previous study primary tumor growth was not affected by the absence of JUNB in the tumor stroma." (PMID 34282521, 2021). "Characterization of the immune cell landscape in JUNB-deficient mice revealed that the metastatic phenotype in stromal JUNB KO mice does not correspond to the increased anti-tumor response observed in regulatory T cell-specific JUNB knockout mice." (PMID 34282521, 2021). "It is interesting that in a patient with available primary tumor and pleura metastasis, the sample from the primary tumor was completely negative for JUNB expression (H-score 0), while in metastasis the H-score was extreme." (PMID 31370904, 2019). "In addition, MSK1 and MSK2 facilitate the stress-induced phosphorylation of CREB at Ser-133, which induces the transcription of several immediate early genes including c-fos, junB, and egr1, which are, notably, part of the low-TTP tumor gene signature." (PMID 25541715, 2014). "In accordance with its role as tumor suppressor, the enforced expression of JUNB suppresses tumor formation and the lack of JUNB lead to a highly aggressive and rapidly progressing disease." (PMID 21789792, 2011). "To verify whether JUNB-overexpressing Huh7, Huh1, or patient HCC cells transform into CD90-positive HCC cells, we subcutaneously implanted them into NOD-SCID immunodeficient mice and observed tumor progression." (PMID 40253402, 2025).
tumor (continued). "Interestingly, JUNB expression was not uniform across each tumor, but rather displayed varying degrees of intratumoral spatial heterogeneity." (PMID 39762215, 2025). "JUNB signaling can be regionally repressed through macrophage-secreted TNF-α, destabilizing favorable CLA-like state and inducing T cell exclusion, which highlights the important role of the single cytokine TNF-α in shaping an immunosuppressive TiME and tumor aggressiveness." (PMID 39762215, 2025). "Moreover, JUNB (JunB proto-oncogene) and NR4A1 (nuclear receptor subfamily 4 group A member 1 gene) can also regulate the functional state of T cells in the TIME, serving as targets of tumor immunotherapy." (PMID 40574864, 2025). "In our study, DUSP5 exhibited intermediate expression relative to JUNB and CDH1, and its expression was lower in cells cultured in the 3LBNC scaffold compared to conventional plate culture, further supporting the scaffold’s ability to replicate features of the in vivo tumor microenvironment." (PMID 40558895, 2025). "Indeed, the trans differentiation of the normal epithelium into duct-like progenitor cells in chronic pancreatitis is mediated by Fra-1/JunB dimers; then, the insurgence of KRASMUT stabilizes AP-1 activation, locking the epithelium in a progenitor state, preceding the tumor initiation." (PMID 38104183, 2024). "As for JUNB, more and more studies have shown that it is involved in tumorigenesis by regulating cell proliferation, differentiation, senescence, and metastasis, and in particular, it affects the TME by transcriptionally promoting or repressing oncogenes in tumor cells or immune cells." (PMID 39430754, 2024). "The IL6/JAK2/STAT3 signaling axis is best studied in the context of tumor metastasis and tumor pathology since it induces epithelial–mesenchymal transition (EMT), resulting in tumor metastasis by promoting the expression of EMT-inducing transcription factors, such as Snail, ZEB1, JunB, and Twist1." (PMID 38203502, 2023). "Under different genotoxic stress, JunB may act as an oncogene or tumor suppressor gene; our discoveries here imply that ATXN3 potentiates JunB oncogenic functions including PD-L1–mediated tumor evasion." (PMID 38038129, 2023). "Together, these results suggest that increased expression of MCL1 and B3GNT2 may promote tumor progression and immune evasion in patients, whereas JUNB is not as clinically relevant across diverse tumor types." (PMID 35338135, 2022). "As a first step to address this point, we tested whether increasing the stimulation time by exogenous TGFB2 of JUNB-overexpressing U2OS cells, which would mimic permanent production of this cytokine in an advanced tumor environment, could affect cell proliferation." (PMID 36494864, 2022). "Indeed, lung vascular density was higher in JUNB KO mice compared to controls, irrespective of primary tumor presence." (PMID 34282521, 2021). "The role of STAT3 in tumor suppression by regulation of JunB has not been made clear but this is an example of a STAT3-regulated gene that may support or suppress tumor growth." (PMID 24743777, 2014). "Furthermore, in pancreatic orthotopic tumor models, low-grade/well-differentiated tumors not only displayed restricted GATA6 and JUNB expression, but also showed a significantly higher number of GATA6:JUNB double-positive cells compared to high-grade/poorly differentiated tumors." (PMID 39762215, 2025). "Notably, JunB is critical for the suppressive functions of Treg cells and regulates key effector molecules such as CTLA-4, which may result in unfavourable inhibition of the anti-tumour response." (PMID 39859271, 2025). "However, the current study is not clear whether JunB promotes or inhibits the effect of NK cells in the tumor microenvironment, and more studies are needed to prove it." (PMID 37731821, 2023).
tumor (continued). "In addition to modulating tumor cell proliferation, senescence, metastasis, and metabolism, an increasing body of evidence suggests that JunB exhibits significant potential in regulating the TME; conversely, the expression levels of JunB are also influenced by the stroma within the TME." (PMID 37731821, 2023). "While absence of JUNB strongly augmented the marker expression of Ptprc (CD45), Itgam (CD11b) and Ly6g in tumor-bearing mice, it hardly had any effect in unchallenged mice, in which only a much smaller rise in Ly6g expression was detected." (PMID 34282521, 2021). "Although JUND and JUNB are often credited with similar tumor promoter/suppressor roles regarding the cellular context, the vast majority of published data (including those in cancer of non-prostatic origin) credit JUND/JUNB with opposing roles to c-JUN." (PMID 41020863, 2025). "For example, we observed that the HOOK2 gene in case 19 was highly expressed in the tumor sample (19T), but not in its matched normal (19N) and stroma (19S) samples, while those genes around HOOK2 (SNORD41, TRIR, and JUNB) had similar levels of expression in all three samples." (PMID 33916417, 2021). "Considering the manifold and intricate functions of the complement system, the correlation between JUNB and individual LR pairs was not sufficient to clarify the complement characters in the TME, to be specific, which activity dominated remained unclear: anti-tumor or pro-tumor?" (PMID 35812726, 2022).
cancer (87 papers, 1995 to 2026). A tumor composed of atypical neoplastic, often pleomorphic cells that invade other tissues. "Given its frequent association with cancer, as well as regulating JUNB, further investigation of the identified miRNAs is warranted." (PMID 39575761, 2025). "Further investigation in larger patient cohorts, as well as other cancer types, is essential to validate the prognostic and diagnostic significance of JUNB, CXCR4, and PD‐L1 in both CTCs and exosomes." (PMID 39575761, 2025). "YAP/TAZ can be recruited by STAT3/JUNB, mediating downstream cellular transformation associated with poor cancer survival." (PMID 39738726, 2024). "TFs of AP-1, regulating TNFα, IL-6 and SELE are implicated as oncogenes or tumor suppressors in many cancers with drug development programs targeting cJun, JunB, JunD, cFos, FosB, Fra1 and Fra2." (PMID 36371231, 2022). "JUNB has also been implicated in the pathogenesis and resistance to chemotherapy of malignant pleural mesothelioma, a highly aggressive human cancer." (PMID 36494864, 2022). "CXCR4, JUNB and PD-L1 are implicated in cancer progression and metastasis." (PMID 38727318, 2024). "In metastatic prostate cancer, the loss of JUNB resulted in increased cancer cell proliferation." (PMID 37717015, 2023). "As expected, we identified that the upregulation of three collagen genes (COL1A1, COL3A1, and COL1A2), BTG2, and JUNB might be responsible for the radiation-associated secondary cancers in patients with BCa." (PMID 35274048, 2022). "We next addressed whether high JUNB levels could be associated with bad prognosis in cancers by analyzing cancer data sets from the publicly accessible TCGA databank with cBioportal for Cancer genomics." (PMID 36494864, 2022). "Oncogenes are a group of mutated genes that may cause cancer, such as JunB and PIM1." (PMID 36479105, 2022). "HCC cells in which JUNB expression was increased by fibroblast-derived TGFb1 were transformed into mesenchymal cancer cells, with potential to metastasize to the lungs." (PMID 40253402, 2025). "ACCEPT software was indicatively used to automatically identify cancer cells, providing simultaneous information regarding the expression level (intensity) of JUNB and CXCR4." (PMID 39575761, 2025). "Coregulations of SOCS3, STAT3, and JUNB have been reported in different contexts as well, thus underscoring the importance of the mechanism in cancer progression." (PMID 41020863, 2025). "JUNB and JUND are two transcriptional factors (TFs) of increased interest in cancer, regulating the expression of genes associated with survival, proliferation, differentiation, migration, invasion, angiogenesis, adhesion, apoptosis, and cell cycle regulation." (PMID 41020863, 2025). "JUNB’s role in senescence has also been mentioned in other cancer types, in which similar mechanisms have been described." (PMID 41020863, 2025). "All these findings combined indicate that both JUNB and JUND are implicated in several cellular processes associated with cancer, either as suppressors of its progression or as promoters." (PMID 41020863, 2025). "Together, our findings suggest that dysregulated Wnt/β-catenin signaling impairs intestinal ILC3s through TCF-1/JunB/RORγt regulation, further disrupting intestinal homeostasis, and promoting inflammation and cancer." (PMID 38561332, 2024). "We exploited the JUNB-dependence of EMT to define a gene signature which is controlled by TGFβ in multiple cancer entities and which is predictive of patient survival." (PMID 36672507, 2023). "In malignancies, such as MM, drug design for JunB will help to develop new strategies to slow down the progress of cancer." (PMID 37731821, 2023). "Among the 23 NFκB/TNF hallmark genes voted in all 16 cancer types, EGR1, JUNB, and ZNF36 exhibited an average vote of 1,000." (PMID 37475016, 2023).
cancer (continued). "For example, RhoA/ROCK and JUNB signaling pathways or SOX4 overexpression, which control NFIX expression both during embryonic development and in the context of cancer, have been linked to oxidative stress." (PMID 36901722, 2023). "In the present study, we have shown that JUNB has important previously uncharacterized roles, not only in the control of cell proliferation, but also in cell invasion/metastatization by cancer cells with an epithelial phenotype." (PMID 36494864, 2022). "Next, we explored the feature of JUNB in anti-cancer immune responses in which a series of progressive events were required to be initiated and enabled to proceed and amplify iteratively." (PMID 35812726, 2022). "Correspondingly, various adaptive and innate immune cells were recruited and highly infiltrated in TME with low-expressed JUNB, and the cancer antigen-presenting step in stepwise anti-cancer immune response was also significantly activated." (PMID 35812726, 2022). "Several cancer-related TFs such as JUNB, JUND, Forkhead box protein M1 (FOXM1), and ETS1 were part of the TF–mRNA regulatory network." (PMID 36232337, 2022). "Strikingly, activities of all steps in the cancer immunity cycle were downregulated in the high-JUNB group." (PMID 35812726, 2022). "In particular, inflammation and cancer-related ERGs (e.g., A20 and JUNB) showed a transient fold change in expression." (PMID 34853340, 2021). "We next performed RNA-ISH in SP-MPE tissue sections of MUV068 and confirmed expression of this marker in all cancer cells, while only a small subpopulation of cells also stained positive for the SP-Progenitor-like marker JUNB in an interspersed manner." (PMID 32663469, 2020). "Combining all these data with our findings strongly supports that JUNB plays a critical role in cancer metastasis." (PMID 31370904, 2019). "Western blotting was performed to study the expression pattern of AP-1 family proteins (c-Jun, JunD, JunB, c-Fos, FosB, Fra-1 and Fra-2) in all spectrum of tongue tissue biopsies from normal, precancer to cancer including TSCC cell lines." (PMID 26581505, 2015). "Based on our findings that PDK1 expression is closely related to the prognosis of GBC, additional studies of PDK1 and JunB as cancer biomarkers are warranted." (PMID 26318166, 2015). "It is also clear that some AP1 transcription factors function as procancer proteins (e.g., c-jun, c-fos), while others inhibit cancer development (e.g., JunB, ATF2)." (PMID 23762562, 2013). "JUNB, as a component of activator protein-1 (AP-1), inhibits the cell cycle and induces senescence, thereby acting as a tumor suppressor in a variety of cancers." (PMID 38674080, 2024). "In the following, we will address the role and regulatory mechanism of JunB in different cancers." (PMID 37731821, 2023). "Therefore, JunB is a crucial transcription factor in HL and ALCL, and it is necessary to explore new drugs targeting JunB to inhibit the progression of these cancers." (PMID 37731821, 2023). "Finally, we verified JUNB in the Human Protein Atlas, the results of which showed that JUNB protein expression was significantly lower in the cancer tissues than in the adjacent normal tissues." (PMID 37501756, 2023). "JunB combines with the sequence of the targeted gene's cis-regulatory domain, thus regulating a variety of biological processes, including cell proliferation, cycle, and apoptosis and plays a role in promoting or suppressing cancer." (PMID 36062065, 2022). "Altogether, our results on JUNB genomic, transcriptomic, and functional studies provide useful information that may be exploited for cancer prognosis and therapy." (PMID 36494864, 2022). "Therefore, in the present study, we have investigated the genome-wide transcriptional effects of JunB in proliferating cancer cells, combined with functional assays." (PMID 36494864, 2022).